CXCL1 (C-X-C motif chemokine ligand 1)
Diseases named in the same sentence as CXCL1 in open-access papers (continued):
Sharing a sentence is not in itself a finding about the gene and the disease.
tumor (continued). "Activation of lung epithelial TLR3 by RNAs in tumor-derived exosomes via NF-kB and MAPK pathways increased the production of chemokines such as CXCL1, CXCL2, CXCL5, and CXCL12, leading to the recruitment and accumulation of neutrophils for PMN formation." (PMID 38495881, 2024). "The axis of CXCL1/CXCR1, a receptor of CXCL1, activated the MAPK kinase pathway to tumor progression." (PMID 38393465, 2024). "CXCL1 and CXCL12 promote tumor cell migration, CXCL5 increases angiogenesis while TNF-α affects immune-mediated clearance." (PMID 38175424, 2024). "Dysbiosis in the breast microbiome can lead to inflammation in breast tissue, increasing M2-like macrophage infiltration, enhancing levels of interleukin (IL)-23, IL-22, CXCL-1, and CCL-2, and accelerating fibrosis within the tumor environment." (PMID 39717276, 2024). "In this study, we revealed that SERPINB3 modulated the TME toward an immunosuppressive phenotype by upregulating CXCL1/8 and S100A8/A9 production to facilitate tumor growth and impede the success of RT." (PMID 37279067, 2023). "Neutrophils are recruited to the tumor (site of injury) through secretion of inflammatory cytokines such as tumor growth factor β (TGFβ), CXCL8 (also known as IL-8), CXCL1, CXCL2 as well as IFNs." (PMID 36910138, 2023). "After stopping gemcitabine treatment, metastatic tumor cells secrete CXCL1 and CXCL2 to attract neutrophils that express growth arrest-specific 6 (Gas6) protein, a ligand of AXL receptor on metastatic tumor cells, resulting in tumor regrowth and progression." (PMID 37173915, 2023). "High expression of CXCL1 can predict the recurrence of HCC in patients and promote tumour progression by increasing tumour cell metabolism and epithelial mesenchymal transformation (EMT)." (PMID 37037815, 2023). "The increase in the number of macrophages in the tumour microenvironment (TME) promoted tumour cell epithelial-mesenchymal transition (EMT) and significantly increased CXCL1 levels in the TME partly through NF-κB/IL-1β activation." (PMID 37037815, 2023). "Macrophages can secrete a variety of cytokines, such as CXCL1, IL6, TGF-β, and VEGF, which can promote tumor growth and metastasis and increase the density of macrophages in the intratumoral region of GC patients." (PMID 36983741, 2023). "Three neutrophil chemokines, CXCL1, CXCL2, and CXCL8 were all found upregulated in the tumor compartment of responders." (PMID 37835599, 2023). "Previous studies have revealed that CXCL1 and its receptor CXCR2 are involved in the angiogenesis, tumorigenesis and metastasis of different types of tumours, such as rectal cancer, breast cancer and HCC." (PMID 37037815, 2023). "Both CXCL1 and CXCL2 are ligands of CXCR2, which promotes tumor growth and progression by inhibiting the cytotoxic activity of CD8+ T cells." (PMID 36713833, 2023). "We further find that epigenetic priming induces increased tumor secretion of several key cytokines known to augment T and NK cell activation and cytotoxicity, including IL-6, IP-10 (CXCL10), KC (CXCL1), and RANTES (CCL5)." (PMID 37627156, 2023). "CXCL1 also induces the recruitment of naive CD4+ T cells, which are transformed into regulatory T (Treg) cells under the influence of the tumor microenvironment." (PMID 37108425, 2023). "In consistency with these studies, ETP-treated and F30-HSCs exhibited higher levels of pro-inflammatory gene expression, such as IL-1β, IL-6, CXCL1 and CXCL9, as well as MMPs (for tumor metastasis) than controls." (PMID 37649614, 2023). "Chemokines produced by tumor cells, immune cells, and tumor stromal cells, including CC­chemokine ligand 2 (CCL2), CCL5, CXC­chemokine ligand 12 (CXCL12, also known as SDF1) and CXCL1, are involved in this process." (PMID 36824409, 2023).
tumor (continued). "Tumor inflammatory cytokines from the primary site like IL-6 and IL-8 attract CTCs and leaky tumor neovasculature allows it to leak back into their primary site, where it secrets MMP-collagenase-1 and CXCL1 which stimulates tumor growth and angiogenesis." (PMID 37031192, 2023). "Intratumoral microbiota enhanced the secretion of specific chemokines (e.g., C-C motif chemokine ligand 2 (CCL2), CCL4, CXCL1 and CXCL10) and interleukins (e.g., IL-1β, IL-6 and IL-10) into the surrounding milieu, leading to T cell exclusion and tumor growth." (PMID 37868956, 2023). "As detected by qPCR, significantly increased mRNA expression levels of CXCL1, CXCL2, CCL5, CXCL10, and IFN-β were detected in tumor tissues isolated from the shIDH3α + CDDP + PD-L1 group compared to the control+CDDP+PD-L1 and shIDH3α groups." (PMID 36980689, 2023). "We measured the expression of CXCL-1 and CXCL-2 in the tumor tissue and detected higher expression of CXCL-1 in Kyse-410 than Kyse-30 tumors while the expression of CXCL-2 was below the detection limit for both tumors." (PMID 37046658, 2023). "Mo0 stimulated the release of cytokines and chemokines such as IL6, IL1A, CXCL1, CXCL5, and CCL20, which can induce monocyte recruitment to tumor." (PMID 37675100, 2023). "Major initiators of tumor inflammation such as CCL2, CXCL1, CXCL2, CXCL11, CSF1, LTB, and TNFSF10 were found to increase in both cell lines, while inflammation suppressors like IL13and IL1RN were decreased." (PMID 36831395, 2023). "The abundances of CXCL1, CXCL2, and CXCL5 in the lungs of C57 mice with EO771 tumor were 38.0-fold, 19.6-fold, and 10.8-fold, respectively, higher than that in the lungs of BALB/c mice with 4T1 cancer." (PMID 37553342, 2023). "CXCL1 expression in cancer cells can be increased by IL-17 and also apolipoprotein E (ApoE) secreted by inflammatory CAF into the tumor microenvironment." (PMID 37408240, 2023). "Expression of chemokine receptors that match ligands secreted by the tumor such as CCL2, CCL22, CXCL16, CX3CL1, CXCL1 and CXCL8 can enable CD8+ T cells to enter the tumor." (PMID 37301772, 2023). "In their study, worse tumor features and poor overall survival in patients with CRC were influenced by CXCL1, CXCL2, CXCL8 and CXCL13, which contributed to CRC treatments." (PMID 37393391, 2023). "CXCR2 ligands, including CXCL5, CXCL2, and CXCL1, produced by TNF-α activated MSCs account for the deposition of neutrophils at tumor primary sites and contribute to the metastatic microenvironment formation." (PMID 38022534, 2023). "In the RM-9 tumor model, radiation increased mRNA levels of CXCL2, CXCL3, and CXCL7 at 24 h post-treatment and the protein levels of CXCL1 and CXCL2 at 24 h and 48 h post-treatment." (PMID 38067390, 2023). "It has been shown that CCL2-CCR2 axis and CXCL1/2-CXCR2 axis are the main pathways that recruit M-MDSCs and PMN-MDSCs, to tumor microenvironments, respectively." (PMID 37932814, 2023). "Low passage tumor alone secreted high concentrations of CCL2/MCP1, CXCL8/IL-8, CXCL1/GRO, IL-6, CXCL10/IP10, G-CSF, TGFβ1, MMP1, CCL3/MIPα, GM-CSF and EGF." (PMID 37063842, 2023). "One of the mechanisms of neutrophil attraction to the TME is the secretion of CXCL1, CXCL2, CXCL5, and CXCL8 by the malignant cells and the tumor stroma." (PMID 36260158, 2023). "Our results indicate that epigenetic priming mediates the rapid secretion of key tumor-derived cytokines known to augment T and NK cell activation and cytotoxicity, including IL-6, IP-10 (CXCL10), KC (CXCL1), and RANTES (CCL5)." (PMID 37627156, 2023). "Increased CXCL1 promotes TAM2 migration by inhibiting the recall of CD4+ and CD8+ T cells at tumor sites." (PMID 37371856, 2023). "The levels of cytokines CCL21, eotaxin, CXCL1, CXCL2, CCL7, CCL19, and CCL25, which are capable of supporting tumor invasion, were reduced in CM from MSCs-TRAIL by 1.2, 1.3, 4-8, 3.4-1.3, 1.5, and 1.3 times, respectively (n = 3, ** p < 0.01)." (PMID 36661524, 2023).
tumor (continued). "CXCL1 and CXCR2 are known to have a regulatory role in tumor cell migration, invasion, and metastasis in a variety of cancers." (PMID 36614235, 2023). "It was also shown that tumor cells through secretion of some mediators, i.e., Prostaglandin E2 (PGE2) and CXCL1/5, led to Th17 expansion and CXCL1 production, and subsequently BC growth and development." (PMID 37835465, 2023). "CXC (such as CXCL1, CXCL2, CXCL5, CXCL6, and CXCL8) at the tumor site involve CXCR2+ neutrophils that differentiate into TANs." (PMID 36980182, 2023). "Irradiation caused the release of γH2AX (a marker of DNA damage), followed by elevated levels of chemokines CXCL1, CXCL2 and CCL5 to recruit TANs to the tumor site." (PMID 37833255, 2023). "The recruitment of MDSCs to the tumor bed is mediated by the expression of CXCR2 ligands, including CXCL1 and CXCL2." (PMID 37865804, 2023). "As for chemokines, such as CCL2, CCL3 and CXCL1, their expressions in GISTs are relatively high and CCL2 induces the infiltration of macrophages into tumor tissues and promotes tumor growth." (PMID 37072770, 2023). "Apoptotic tumor cells can release chemokines CXCL1/CXCL2, recruit neutrophils in peripheral blood and induce them to change into N1‐type neutrophils with killing activity, thus completely removing tumor cells." (PMID 35861052, 2023). "Metformin mediates the PMN-MDSCs reduction in the tumor via activation of AMPK, which upregulates dachshund homolog 1 (DACH1) expression on tumor cells and, therefore, downregulates CXCL1 expression." (PMID 37686159, 2023). "Conditioned tumor cell medium treated with 10 μM 5-aza showed upregulation of 4 key cytokines—IL-6, IP-10 (CXCL10), KC (CXCL1), and RANTES (CCL5)—which activate both adaptive and innate immune responses." (PMID 37627156, 2023). "CXCL1 derived from TAMs/CAF can play a favorable role in regulating intercellular adhesion and the crosstalk among tumor cells and TAMs/CAF and further results in an increased tumor proliferation in a paracrine manner." (PMID 35764974, 2022). "CXCL1 and CXCL2 produced by tumour cells can promote the generation of monocytic myeloid-derived suppressor cells." (PMID 35468838, 2022). "While CXCL1 and CXCL10 levels significantly decreased after tumor resection, postoperative CXCL13 levels were significantly higher compared to preoperative values." (PMID 36077611, 2022). "Our prior work identified a paracrine inflammatory loop in breast cancers that disrupts the microenvironment of both the tumor and surrounding myeloid cells and involves TNF-α, CXCL1/2, and S100A85." (PMID 36241629, 2022). "Murine orthologs of CXCL8 with functions that partially overlap with pro-tumorigenic IL-8 functions are CXCL1/KC and CXCL2/MIP2, which promote mouse tumor growth and angiogenesis." (PMID 36522309, 2022). "The activation of Stat3 induced the secretion of glutamic acid-leucine-arginine (ELR) motif CXCLs (CXCL1, CXCL2, CXCL3 and CXCL8) in tumor cells." (PMID 35280694, 2022). "Based on the promising findings on the prognostic relevance of baseline CXCL13 serum levels, we subsequently evaluated the potential regulation of CXCL1, CXCL10 and CXCL13 after tumor resection." (PMID 36077611, 2022). "Compared to fibroblasts from normal tissues, the top upregulated genes in tumor-derived fibroblasts were CXCL8, CXCL2, CCL2, CXCL3 and CXCL1, and the top downregulated genes were IGFBP5, PTGDS, CCN5, CFD, and RAMP1." (PMID 36357663, 2022). "To detect the effect of CXCL1 on the tumor microenvironment, we examined CD4, CD8, and CD163 expression in tumor tissues of each group of mice." (PMID 36434686, 2022). "The CXCL1 and CXCL2 derived from BMAs were shown to promote prostate cancer survival and stiffen the overall tumor immune response." (PMID 35800430, 2022). "CXCL1 and CXCL2, highly expressed in several tumor cells, increase the generation of monocytic MDSC that inhibits T cell proliferation." (PMID 35163097, 2022).
tumor (continued). "While CXCL11 is a chemokine that mainly attracts activated T cells, allowing them to migrate to tumour sites and suppress tumours, CXCL5 and CXCL1 are chemokines with chemotactic and neutrophil-activating functions." (PMID 35740353, 2022). "To evaluate the potential roles of CXCL1 in UCC biology, we employed recombinant CXCL1, CXCL1-overexpressing HeLa, and PHM1-41 cells to derive the effects of CXCL1 on HeLa tumor cell malignant behaviors." (PMID 35764974, 2022). "In order to validate this assumption, the cytokines for neutrophil recruitment, including CXCL1 and CXCL2, were examined in the cisplatin-treated tumor cells." (PMID 35784745, 2022). "We next compared the circulating levels of CXCL1, CXCL10 and CXCL13 between BTC patients with different tumor and clinical characteristics." (PMID 36077611, 2022). "DARC can internalize chemokines (i.e., CCL2, CCL11, CXCL1, CXCL2, CXCL3, CXCL5, CXCL7, CXCL8) that promote angiogenesis or formation of blood vascular, which can foster tumor growth, as well as promote endothelial cell survival via inhibiting apoptosis." (PMID 36497078, 2022). "The tumor and mesenchymal cells in the TME express multiple chemokines and cytokines (e.g., CXCL1, CXCL2, CXCL5, CXCL6, IL1, IL1β, IL6, IL8, IL17, TNFα, and G-CSF), which are regulated by KRAS, SNAIL, and NOTCH signaling." (PMID 35504900, 2022). "Another study reported that overexpression of CXCL1 stimulates CXCR2+ endothelial cell migration and increases the formation of tumor microvessels in CRC patients." (PMID 35954156, 2022). "Neutrophil-attracting chemokines, such as CXCL1, CXCL2, or CXCL8, are induced in hypoxic tumor tissue, through the activation of hypoxia-inducible factor 1 (HIF-1α or β), and support neutrophil migration to the tumor site via CXCR1 and CXCR2 receptors." (PMID 35158807, 2022). "More specifically, we have detected increased levels of sICAM-1, CXCL10, CXCL1, CCL5, TIMP-1 and TNFα in tumours treated with VV-αCEA TCE, compared to tumours treated with VV-CTRL or PBS." (PMID 36405739, 2022). "Once they reach the tumor site, TANs secrete a vast set of factors potentially involved in the biology of CCA (such as MMP-8, MMP-9, CXCL1, CXCL2, CXCL6, CXCL8, CCL7, and VEGF)." (PMID 39301518, 2022). "Knockdown of SMAD4 from human CRC cells enhances CXCL1 and CXCL8 expression and accumulates CXCR2+ neutrophils to CRC tumor." (PMID 35935996, 2022). "We detected more abundant levels of sICAM-1, CXCL10, CXCL1, CCL5, TIMP-1 and TNFα in tumours treated with VV-αCEA TCE, compared to tumours treated with VV-CTRL or PBS." (PMID 36405739, 2022). "CXCL1 stimulates FAK, PI3K and Akt which in turn activates the IKKα/β complex to trigger p65 via the activation of IkBα for tumor cell proliferation." (PMID 35954156, 2022). "Inversely, tumor exosome anti-metastatic miR-192 significantly attenuates tumor metastasis by suppressing the expression of angiogenic factors such as IL-8, intercellular cell adhesion molecule (ICAM), and C-X-C motif chemokine ligand 1 (CXCL1)." (PMID 35562884, 2022). "Similar to CXCL1, CXCR2 inhibition decreases the CXCL2-induced neovascularization and tumor progression." (PMID 35954156, 2022). "Across serum, conditioned media and both tumor types, four factors are consistently detected: CCL2, CXCL1, CXCL10 and Serpin E1." (PMID 35962398, 2022). "This emphasised the key association of D14 neutrophils, PD-L1+ myeloid cells and Ly6Cintermediate monocytes with CT26 tumour size, and a more distant relationship with D7 myeloid cells, CCL17, CXCL1, CCL2, CXCL10 levels, and D14 IL-10 level." (PMID 35226704, 2022). "Immature DCs can be recruited into the TME, attracted by tumor-secreted factors such as CCL2, CCL20/MIP3a, CCL25, CCL5, CXCL12, CXCL1, and CXCL5, while mature DCs reside in areas surrounding the tumor." (PMID 35267487, 2022).
tumor (continued). "These correlations change with time, with early low expression of CCL17, CXCL1 and CCL2 eventually promoting myeloid cell development that maintains/promotes larger tumours." (PMID 35226704, 2022). "ELR+CXCL cytokines (CXCL1, 2, 3, 5, 6, 7, 8), which have the amino acid triplet glutamic acid-leucine-arginine (ELR) in their amino-terminal domain, are indeed involved in tumour growth, invasion, and metastasis formation." (PMID 36497191, 2022). "The COX-2/PGE2 pathway induces IL-11, chemokine (C-X-C motif) ligand CXCL-1, CXCL-2, and CXCL-5, which help to promote tumor growth and maintain cancer cell stemness." (PMID 35892729, 2022). "Consistently, THP-1 macrophages treated with CM of tumor cells or CM of olaparib-treated tumor cells showed significantly up-regulated IL6, IL1B and CXCL1 gene expression." (PMID 35641483, 2022). "Several chemokines (CCL2, CXCL1, CXCL2, CXCL10) were also increased in MC38 and CT26-conditioned media and tumor-bearing mouse serum." (PMID 35962398, 2022). "In both CRC subtypes, the pro-inflammatory cytokines IL1-β, IL-6 and TNF upregulate the chemokines CXCL-1/2/3/5/6/8 in CAFs, monocytes and cancer cells; this attracts CXCR1/2-positive neutrophils to the tumor." (PMID 36611932, 2022). "CXCL1 can directly recruit circulatory CXCR2-expressing neutrophils and MDSCs from the circulation into inflammatory sites and tumor tissues, promoting liver metastasis." (PMID 35954156, 2022). "The results showed that CXCL1 gene was correlated with preoperative CEA level (P=0.007) and gross tumor typing (P=0.039)." (PMID 35958781, 2022). "In summary, we demonstrated that HOXA7 overexpression upregulated CXCL1 expression, facilitating the recruitment and infiltration of MDSCs into the KRAS mutant CRC tumor niche." (PMID 35183163, 2022). "CHMP2B, CHMP6, and RIPK3 were downregulated, while CXCL1, GPX4, and TRAF2 were upregulated in tumor samples." (PMID 36046241, 2022). "Mast cells are recruited by the microenvironmental chemokines, such as CCL2, CXCL1, CXCL8/IL8, and CXCL10, to tumor tissues, and are activated by pro-inflammatory cytokines, such as stem cell facto (SCF), IL33, PGE2, leukotriene B4, and osteopontin, in there." (PMID 36211375, 2022). "IL-8 binds to its receptor CXCL1/CXCL2 and promotes angiogenesis, proliferation, and the invasion of tumor cells." (PMID 35892729, 2022). "In BlCa, IL-6, CCL2, CXCL1, CXCL12, IL-8 and TGF-β1 play putative roles in promoting tumor progression, growth, invasion, and metastases formation." (PMID 36699696, 2022). "At the same time, IL-17A induces the production of CXCL-1 and CXCL-5, leading to the recruitment of the expanded myeloid cells into the tumor where they help to establish a tumor promoting microenvironment." (PMID 36611932, 2022). "Levels of VEGF, CXCL-1 and IL-1β were also markedly lower in inflammatory AOM/DSS tumours of Gpr35ΔMΦ compared with Gpr35fl/fl mice." (PMID 33758004, 2022). "Mice with 4T1 tumours also had a subtler increase in CXCL13 relative to normal levels, and a subtle increase in IL-6 and a subtle decrease in CXCL1 compared to CT26-bearing animals." (PMID 35226704, 2022). "The roles for the chemokines CXCL1 and CXCL2 in tumor promotion has been mentioned in many studies, such as promoting epithelial-mesenchymal transition (EMT), invasiveness, metastasis, and cell survival under chemotherapy." (PMID 36411463, 2022). "Neutrophils bear receptors for a number of neutrophil chemokines, including CXCL1 and CXCL2, that are formed following surgical stress but are also expressed on some tumor cells." (PMID 34899751, 2021). "Both NDN and LDN were found to migrate in response to CXCL1 and CXCL2 exposure, and co-infiltrate the tumor site ex vivo and in vivo, although LDN migration into the tumor was higher than NDN." (PMID 34680231, 2021).